RNU1-52P (RNA, U1 small nuclear 52, pseudogene)
Gene: Small nuclear RNA gene on chromosome 17 (58,677,574 to 58,677,737, reverse strand). Ensembl gene ENSG00000206917.
Homologues: Orthologues: chimpanzee U1 (98% identical), macaque U1 (91% identical), guinea pig U1 (66% identical), rat U1 (61% identical), mouse Gm22145 (60% identical), rat U1 (47% identical). Paralogues in human: RNU1-1 (84% identical), RNU1-2 (84% identical), RNU1-27P (84% identical), RNU1-28P (84% identical), RNU1-3 (84% identical), RNU1-4 (84% identical), RNVU1-18 (84% identical), RNVU1-29 (84% identical), U1 (84% identical), RNU1-67P (83% identical), RNU1-89P (83% identical), RNVU1-28 (83% identical), and 133 more.